BRCA2 (BRCA2 DNA repair associated)
Diseases named in the same sentence as BRCA2 in open-access papers (continued):
Sharing a sentence is not in itself a finding about the gene and the disease.
leukemia (27 papers, 2007 to 2025). A malignant (clonal) hematologic disorder, involving hematopoietic stem cells and characterized by the presence of primitive or atypical myeloid or lymphoid cells in the bone marrow and the blood. "BRCA2 accounts for 50% (7/14), with P/LP variants including a variety of tumors in relatives such as breast, thyroid, bone, gastric, prostate, leukemia, and esophagus, followed by ATM, in 3/14 (21.4%), which referred on thyroid, gastric, and brain cancers." (PMID 38890714, 2024). "Low levels of BRCA2 in poor prognosis pediatric AML clusters also aligns with findings of increased risk of leukemia in patients with BRCA2 mutations." (PMID 36982970, 2023). "BRCA1 and BRCA2 mutations increased leukaemia (RR 2.3 [1.21–4.39] and 1.79 [1.03–3.12], respectively)." (PMID 34577828, 2021). "BRCA2 pathogenic variants were found in 4 patients (0.5%), with diagnoses including CNS tumors, Wilms’ tumor and leukemia." (PMID 33674644, 2021). "Both BRCA1 and BRCA2 mutation positive families included cases of leukemia that accounted for about 2 percent of affected individuals." (PMID 18783588, 2008). "Some epidemiologic studies show increased risks for leukemia/lymphoma in identified BRCA1 or BRCA2 mutation carriers and in large populations eligible for mutation testing." (PMID 17683622, 2007). "BRCA1 and BRCA2 mutations can increase leukaemia incidence based on three studies." (PMID 34577828, 2021). "BRCA2 deficiency may predispose leukemia cells to synthetic lethality triggered by PARP1 inhibitors." (PMID 31537905, 2020). "The incidence of leukemia is even higher in the FANCD1/BRCA2 subtype of FA, with most cases occurring at less than 5 years of age." (PMID 38203823, 2024). "Five of these compounds representing 3 different chemotypes selectively inhibited growth of BRCA1-, BRCA2-deficient human cancer cells and BRCA1-deficient (with low expression level) primary cells from leukemia patients." (PMID 27649245, 2016). "For example, genes in the BRCA family control specific rearrangements detected in lymphomas and leukemias, and inactivation of BRCA2 leads to an elevation of chromosomal rearrangement in fetal liver cells." (PMID 20603075, 2010). "Because of connections between Fanconi proteins and leukemias, these relationships further implicate BRCA1/BRCA2 deficits in leukemias." (PMID 17683622, 2007). "The situation is different for oncologic BRCA-mutated patients, treated with chemotherapy or not, for whom a risk of developing secondary leukemia/lymphoma is significant, in particular for BRCA2-mutated patients." (PMID 33794974, 2021). "The distinct clinical phenotype of D1 and N patients (severely affected, often combined with leukemia or solid tumors below the age of 5 years) may provide a clue to favor BRCA2/FANCD1 and PALB2/FANCN as the first gene to be screened." (PMID 22778927, 2012). "Cases in group FA-D1 (mutated in BRCA2) and FA-N (mutated in PALB2) present with a distinct, relatively severe, phenotype that is characterized by the development of leukemia at very young age (median 2.2 years) and by pediatric cancers such as nephroblastoma (Wilms tumor) or medulloblastoma." (PMID 22778927, 2012). "The present study was designed to test the hypothesis that inactivation of virtually any component within the pathway containing the BRCA1 and BRCA2 proteins would increase the risks for lymphomas and leukemias." (PMID 17683622, 2007). "Family history of leukemia was observed in patients carrying a VUS in the ATM, BRCA1 and BRCA2 genes." (PMID 37277882, 2023). "In contrast, recent studies have shown that in BRCA-proficient leukemia cells, inhibition of the TGFβ pathway promotes a reduction in ATM, BRCA1 and BRCA2 and a concomitant increase in olaparib sensitivity." (PMID 34871431, 2021). "BRCA2 has been defined as a part of important pathway to prevent a subgroup of human leukemias and lymphomas that may involve non-random, characteristic gene rearrangements." (PMID 25913414, 2015).
Obesity (27 papers, 2007 to 2026). Accumulation of substantial excess body fat. "Genetic factors, BRCA2 mutations, family history, obesity, Klinefelter’s syndrome, gynecomastia, liver disease, orchitis, undescended testicle, alcohol use, exogenous estrogen and testosterone use, and radiation are accused in the etiology." (PMID 32525214, 2020). "Thus, to improve clinical management of BRCA1 and BRCA2 mutation carriers is necessary a deep knowledge concerning the impact of modifiable factors, as obesity, on BC risk, that may provide the oncologists additional recommendations for the care of patients with BC." (PMID 40523654, 2025). "While the risks of MBC from obesity have not been quantified, we propose that men at risk from MBC, e.g., those with BRCA2 mutations or suffering from Klinefelter syndrome, should be made aware of the relative risk between MBC and obesity to take pre-emptive measures to reduce this risk." (PMID 26044503, 2015). "With one-sided 95% CI, power was sufficient to exclude OR ≥2.0 with obesity for ATM and BRCA2; smoking and alcohol for CHEK2; no breastfeeding for ATM; no oophorectomy for BRCA2 and CHEK2; no tubal ligation for CHEK2; and neighborhood socioeconomic status for all genes." (PMID 40298171, 2025).
ductal carcinoma in situ (26 papers, 2005 to 2025). "Apart from intraductal carcinoma, the somatic loss of both alleles of the BRCA2 gene and increased genomic instability and copy number alterations have also been associated with the cribriform pattern and the ductal type of adenocarcinoma." (PMID 37511177, 2023). "BRCA2-mutated tumors have unfavorable clinical and pathological characteristics, such as intraductal carcinoma." (PMID 37511177, 2023). "All patients with intraductal carcinoma present a BRCA2 mutation, also found in 80% of cases with a cribriform pattern." (PMID 35326693, 2022). "In our study, both the tested patients with intraductal carcinoma present a mutation in BRCA2 also found in 80% of the NGS tested cases with a cribriform pattern." (PMID 35326693, 2022). "We reviewed the association between the BRCA2 variant in different histologic subgroups and found the effect most pronounced in women who had ductal carcinoma in situ (DCIS) with micro-invasion (OR = 2.8; p < 0.0001)." (PMID 16280055, 2005). "BRCA2 carriers were more likely to be diagnosed with ductal carcinoma in situ (18.5% vs. 4.4%, p < 0.001) compared to BRCA1 carriers." (PMID 40275390, 2025). "This dysregulation is enriched in BRCA2-mutant PCa harbouring intraductal carcinoma (IDC)." (PMID 28067867, 2017). "For example, the risk for developing breast cancer can be estimated using mathematical models such as the Gail model, identifying the presence of pre-invasive lesions such as ductal carcinoma in situ, or detecting genetic conditions such as BRCA1 or BRCA2 mutations." (PMID 24212828, 2011).
glioma (25 papers, 2011 to 2026). A benign or malignant brain and spinal cord tumor that arises from glial cells (astrocytes, oligodendrocytes, ependymal cells). "The frequency of heterozygous ClinVar pathogenic BRCA2 GVs in unselected adult glioma patients ranged from 3/764 (0.4%) to 3/152 (2%), compared to 5/206 (2.4%) glioma patients with presumed tumor predisposition analyzed here." (PMID 41546701, 2026). "RAD51 expression and the BRCA2 axis are new molecular targets for sensitizing glioma cells to alkylating anticancer drugs and are associated with DNA damage response (DDR)." (PMID 35884836, 2022). "According to the COSMIC database, BRCA2 somatic mutations have been reported in glioma (BRCA2R18H), squamous cell carcinoma of the head and neck (BRCA2M784V), and squamous cell carcinoma of the skin (BRCA2P3292L)." (PMID 29802286, 2018). "From these analyses we have provided evidence to implicate BRCA2 p.(Lys3326Ter) as well as IDH2 p.(Arg261His) as determinants of glioma risk." (PMID 26264438, 2016). "The mean nuclear IRS of PARP1 was significantly higher in gliomas from BRCA2 GV carriers than in those from ATM GV carriers." (PMID 41546701, 2026). "The genes implicated in glioma risk play roles in DNA damage response, e.g., ATM, BRCA2, PMS2, POLE, or diverse other processes including metabolism, signal transduction, and cell cycle regulation." (PMID 41546701, 2026). "All BRCA2 GVs identified here were LoF variants resulting in a reduced BRCA2 expression and an increased PARP1 expression, on average, in glioma sections compared to gliomas from non-BRCA2 GV carriers, thus impacting the molecular tumor phenotype." (PMID 41546701, 2026). "TMZ is an important chemotherapy agent acclaimed as the gold standard for the treatment of GBM and in a previous report, it was shown that glioma cells considerably became more sensitive to temozolomide treatment after BRCA2 knockdown." (PMID 34345539, 2021). "For all glioma, BRCA2 p.(Lys3326Ter) carrier status conferred an OR of 1.76 (P=0.0026), principally associated with GBM (OR=2.3, P=4.0x10−4)." (PMID 26264438, 2016). "The data provides evidence that down-regulation of Rad51 or BRCA2 is a reasonable strategy for sensitizing glioma cells to killing by O6-alkylating anti-cancer drugs." (PMID 22073281, 2011). "For down-regulation of HR in glioma cells, we used an interference RNA (iRNA) approach targeting Rad51 and BRCA2, and for NHEJ we employed the DNA-PK inhibitor NU7026." (PMID 22073281, 2011). "Blood–brain barrier penetrant PARP inhibitors may be effective in glioma patients carrying GVs in ATM, BRCA2, BRIP1, FANCA, and SDHA identified here that are associated with HRR deficiency, and may act synergistically with radio-, chemo-, and immunotherapy." (PMID 41546701, 2026). "BRCA2 GVs (n = 5) were also significantly enriched in glioma patients in approach 2 (P = 0.005)." (PMID 41546701, 2026). "The BRCA2 gene, which encodes an essential homology-directed DNA DSB repair factor, was one of 10 affected CPGs involved in DNA damage response, making up 37% of all mutated CPGs, and was implicated in adult glioma risk using both approaches." (PMID 41546701, 2026). "BRCA2 GV carriers were most frequently affected by glioma between the age of 50 and 65 years." (PMID 41546701, 2026). "Moreover, knockdown of BRCA2 greatly sensitizes glioma cells to DNA double strand breaks and the induction of cell death following temozolomide and nimustine treament." (PMID 25481245, 2014). "The expression of O6-methylguanine-DNA methyltransferase (MGMT) abolished all these effects, indicating that O6-alkylguanine induced by these drugs is the primary lesion responsible for the formation of DSBs and increased sensitivity of glioma cells following knockdown of Rad51 and BRCA2." (PMID 22073281, 2011).
glioma (continued). "Interestingly, the analysis of GBM dataset from TCGA revealed a highly significant inverse correlation between hHSS1 and BRCA2 expression, and that the levels of BRCA2 expression on HSS1-high gliomas were also significantly lower than on HSS1-low expression gliomas." (PMID 25481245, 2014). "Therefore, the combination of such a loco-regional delivery system and the simultaneous down-regulation of FANCD1/BRCA2 could be an effective tool to enhance chemotherapy results for glioma patients." (PMID 21573016, 2011). "Gliomas from SDHA GV carriers with less DSB accumulation showed a trend towards a higher mean nuclear IRS of RAD51 than those from ATM, BRCA2, and FANCA GV carriers with more DSBs." (PMID 41546701, 2026). "Our study presents that BRCA1, BRCA2 and RAD51 are increased in the two glioma cell lines following treatment with TMZ." (PMID 25337721, 2014). "Given the findings that HR-DNA repair proteins (BRCA1, BRCA2 and RAD51) are significantly increased in TMZ-resistant glioma cells, an abundance expression of BRCC3 in glioma cells seems likely to foster HR-dependent DNA repair processes." (PMID 25337721, 2014). "Here we investigate the role of 10 potential SNPs in XRCC3, BRCA2, RAG1, XRCC5, LIG4, XRCC4 and ATM in the development of gliomas, and further evaluate their gene-gene and gene-environment interactions in the development of glioma." (PMID 23663450, 2013). "A semi-quantitative analysis of ATM and BRCA2 staining revealed a trend towards a lower mean nuclear IRS for ATM in gliomas from ATM GV versus non-ATM GV carriers, and for BRCA2 in gliomas from BRCA2 GV versus non-BRCA2 GV carriers." (PMID 41546701, 2026). "The CPGs most frequently affected by GVs were ATM in 6/206 (2.9%) families, BRCA2 in 5/206 (2.4%) families (identified in approaches 1 and 2), GBA1 in 4/206 (1.9%) families as well as EGFR, GJB2, and SDHA in 3/206 (1.5%) families each of the glioma cohort." (PMID 41546701, 2026). "Pathogenic GVs in BRCA2 were detected in five families of the glioma cohort but not in controls (P = 0.005), implicating BRCA2 using both approaches utilized here." (PMID 41546701, 2026). "Besides, BRCA2 was essential for homologous recombination (HR)‐dependent double‐strand break (DSB) repairing pathway and thus participated in glioma resistance to alkylating agents." (PMID 35285582, 2022). "In addition, BRCA1, BRCA2 and RAD51 are required for HR-dependent DNA repair pathway in TMZ-resistant glioma." (PMID 25337721, 2014). "We genotyped 10 potentially functional single nucleotide polymorphisms (SNPs) in 7 DNA double-strand break repair pathway genes (XRCC3, BRCA2, RAG1, XRCC5, LIG4, XRCC4 and ATM) in a case–control study including 384 glioma patients and 384 cancer-free controls in a Chinese Han population." (PMID 23663450, 2013). "Furthermore, other recent studies showed that BRCA2 (FANCD1) plays a predominant role in the repair of DNA damage induced by TMZ, and inhibiting BRCA2 sensitize the glioma cell lines to TMZ treatment, suggesting that BRCA2 is also a molecular target for overcoming TMZ resistance." (PMID 23227453, 2012). "The mean nuclear IRS of phospho-H2AX indicating DSB accumulation was lowest in gliomas from SDHA versus ATM, BRCA2, and FANCA GV carriers, although the differences were not statistically significant, possibly because SDHA variants are least directly linked to impaired DSB repair." (PMID 41546701, 2026).
pancreatic adenocarcinoma (25 papers, 2011 to 2025). "We report here a 33-year-old Asian woman with extensively metastatic pancreatic adenocarcinoma harboring a germline BRCA2 nonsense mutation who a durable response to fuzuloparib after NALIRIFOX chemotherapy." (PMID 40994638, 2025). "In unselected cases of pancreatic adenocarcinoma, pathogenic mutations in BRCA2 are identified in up to 2%, while mutations in BRCA1 are observed in 1% or less." (PMID 38809921, 2024). "A phase II study of olaparib monotherapy in patients with various metastatic malignancies and germline BRCA1/BRCA2 mutations included 23 patients with pancreatic adenocarcinoma." (PMID 36975505, 2023). "To explore this question, we employed pancreatic adenocarcinoma Capan1 cells with mutations in the BRCA2 gene." (PMID 33922657, 2021). "The compound disrupts RAD52-ssDNA interactions and selectively eliminated BRCA2-mutated pancreatic adenocarcinoma Capan1 cells at the concentration range 10–40 μM, whereas the BRCA2-proficient BxPC3 cell line viability was not significantly influenced." (PMID 31615159, 2019). "BRCA2 mutation carriers are at increased risk for multiple cancers including pancreatic adenocarcinoma (PAC)." (PMID 26844277, 2015). "Capan-1 is a well-characterised BRCA2-deficient human cell line isolated from a liver metastasis of a pancreatic adenocarcinoma." (PMID 21750719, 2011). "Similarly to A5MP, AICAR was able to eliminate BRCA1-deficient HCC1937 cells and BRCA2-deficient Capan1 pancreatic adenocarcinoma cells." (PMID 31615159, 2019). "Interestingly, 25% of tumors from patients with pancreatic adenocarcinoma harbored a BRCA2 mutation." (PMID 28028924, 2017). "In a report of resected pancreatic adenocarcinoma, patients with germline BRCA1/BRCA2 and PALB2 mutations had better overall survival (OS) than patients without such mutations (median OS 46.6 months versus 23.2 months)." (PMID 36975505, 2023). "Rucaparib was tested in a phase II trial in 16 germline BRCA1 (n= 12)/BRCA2 (n = 4) mutant pancreatic adenocarcinoma patients and 3 additional patients with somatic BRCA2 mutations who had received one or two chemotherapy lines." (PMID 36975505, 2023). "Capan‐1 cells derived from a pancreatic adenocarcinoma carry a C‐terminal BRCA2 truncation, which impairs RAD51 nuclear localisation." (PMID 31273933, 2019). "We then used BxPC-3, a pancreatic adenocarcinoma cell line expressing a functional BRCA2." (PMID 35955488, 2022). "Importantly, as BRCA2 is a tumor suppressor, replication stress in BRCA2-defective pancreatic adenocarcinoma CAPAN-1 cells was alleviated by overexpression of RNaseH1." (PMID 28098815, 2017). "In the pancreatic adenocarcinoma cases of the project GENIE, which included 5262 cases profiled, the most prevalent oncogenic or likely oncogenic mutations in DDR-related genes were in ATM and in BRCA2, followed by lower frequencies in BRCA1, PALB2, ATR and BRIP1 and a few cases in other genes." (PMID 36975505, 2023). "We also found that germline BRCA2 variants were associated with higher SNV and indel neoantigen loads in pancreatic adenocarcinoma (PAAD, FDR = 2.9 × 10−18, < 1.0 × 10−50)." (PMID 34095878, 2021). "Two patients received therapies following the recommendations of the local molecular tumor board, as mutations with only low or no levels of evidence for actionability were detected (BRCA2 S497L in pancreatic adenocarcinoma; ERBB3 G284R in CCC)." (PMID 38664720, 2024).